PIK3CA (phosphatidylinositol-4,5-bisphosphate 3-kinase catalytic subunit alpha)
Diseases named in the same sentence as PIK3CA in open-access papers (continued):
Sharing a sentence is not in itself a finding about the gene and the disease.
ovarian carcinoma (223 papers, 2003 to 2026). A malignant neoplasm originating from the surface ovarian epithelium. "The activation of NF-κB/TNF-α /PIK3CA signaling pathway increases CSCs, causing resistance to cisplatin in ovarian cancer." (PMID 39919692, 2025). "In particular, in ovarian cancer it is described the mutation H1047R in PIK3CA that encodes for p110alpha subunit of PI3K." (PMID 40370432, 2025). "PIK3CA mutations are frequently observed across various malignancies, including breast cancer, endometrial cancer, and ovarian cancer, highlighting the potential of PI3Ki as a promising therapeutic strategy." (PMID 40573322, 2025). "Alpelisib has also been employed in advanced gynecologic malignancies harboring PIK3CA mutations, including ovarian cancer." (PMID 41383608, 2025). "In ovarian cancer cells, the PIK3CA gene that encodes type I PI3Ks P110α is frequently mutated, which is the reason for the reduced sensitivity of tumor cells to chemotherapeutic drugs." (PMID 38238825, 2024). "In ovarian cancers, PIK3CA mutations seem to be the primary somatic mutations, comprising approximately 12% missense mutations in epithelial ovarian cancers while PIK3R1 mutations are found in 3.8% of ovarian cancers." (PMID 38396649, 2024). "The research sequencing 410 genes of 82 ovarian carcinomas showed that gain of PIK3CA was characteristic of HGSOC, with H1047R/L being the mutation hotspot." (PMID 39104720, 2024). "PIK3CA mutation or gene amplification was detected in 30% of all ovarian cancers and 45% of the endometrioid and clear cell subtypes." (PMID 38391958, 2024). "The theory proposed by Anglesio is consistent with this, demonstrating that in cases of ovarian cancer associated with endometriosis carrying activating PIK3CA mutations, the same mutations repeatedly appear in both cancer and endometriotic specimens." (PMID 39768828, 2024). "In ovarian cancer, 4 out of 260 cases (1.52%) with multiple PIK3CA mutations showed PTEN mutations compared with 4 out of 53 cases (7.55%) with a single mutation." (PMID 39054873, 2024). "PIK3CA mutations are also associated with poor response to platinum-based chemotherapy and platinum resistance in patients with ovarian cancer." (PMID 39695768, 2024). "Genomic alterations of ARID1A and PIK3CA have been detected in 30–60% of endometriosis-associated ovarian carcinomas, that is, endometrioid and clear cell ovarian carcinomas." (PMID 38201563, 2023). "Circulating tumor DNA (ctDNA) allows non-invasive detection of ovarian cancer mutations, such as PIK3CA and KRAS, with potential as diagnostic and prognostic markers in liquid biopsy." (PMID 37629546, 2023). "BRAF V600E and PIK3CA E542K were predominantly associated with thyroid cancer and ovarian cancer, respectively, whereas ERBB2 amplification, BRCA1/2 variant, and KRAS G12C were widely detected across various cancer types." (PMID 36088851, 2022). "In ovarian cancer cases, 25 cases showed PIK3CA mutation in at least a tumor, Pap smear, or plasma sample." (PMID 34172890, 2021). "In this study, we examined PIK3CA hotspot mutations in eutopic endometrium in ovarian cancer, especially OCCC, and endometriosis cases by ddPCR and compared them with mutations in tumors." (PMID 34172890, 2021). "For example, PIK3CA is classified as class A in breast, lung, colorectal, and ovarian cancers, and PIK3CA inhibitors are used in clinical trials for the treatment of PIK3CA-mutated cancers." (PMID 34830205, 2021).
ovarian carcinoma (continued). "In Wang’s cohort, 159 cases of HGSOC were included among 201 cases of ovarian cancer, and tumor PIK3CA mutations were found in only two cases (1.2%)." (PMID 34172890, 2021). "PARP inhibitors further synergize with inhibitors of the PI3K pathway, as shown in BRCA-proficient TNBC, BRCA1 mutated breast cancer mouse models, PIK3CA mutated ovarian cancer cells, and PTEN mutated endometrial cancer cells." (PMID 32029455, 2020). "Herein, we revealed that ovarian cancer cells with PIK3CA/PTEN mutations are sensitive to PI3K/Akt inhibitors; this finding is mainly consistent with those obtained in breast or prostate cancer cells." (PMID 32194423, 2020). "Aberrant activation of PI3K (e.g., PIK3CA mutations), which is detected in many ovarian cancers, can result in inhibitory phosphorylation of GSK3β, rendering it unable to phosphorylate β-catenin and thus ultimately preventing β-catenin degradation." (PMID 32560059, 2020). "Colon and ovarian cancer cell lines had a high frequency of the PIK3CA mutation of 28.57% (2/7) followed by invasive breast carcinoma [20% (1/5)]." (PMID 31289610, 2019). "All four cases that had the PIK3CA mutation were in stage IA of ovarian cancer and all of them also had the KRAS mutation." (PMID 31030485, 2019). "These genes are frequently altered, such as PIK3CA mutation or amplification in up to 30% ovarian cancer patients, while PTEN expression was lost in up to 40% of patients." (PMID 30701134, 2019). "On the other hand, studies on breast and ovarian cancer demonstrated that the patients with the PIK3CA mutation showed a trend towards a favorable prognosis." (PMID 30115035, 2018). "Of the three PIK3CA variants, the missense variant His1047Arg occurred in two samples and has been associated with ovarian cancer in 91 tumors in the COSMIC database." (PMID 28611940, 2017). "The other major gynecological cancers, endometrial and ovarian cancer, share with cervical cancer high rates of PIK3CA mutations and APOBEC and signature 1B mutational signatures." (PMID 28771191, 2017). "While all four ovarian cancer cell lines examined in this study carry PIK3CA mutations, they showed differential responses to combination treatment with BKM120 and Olaparib." (PMID 26909613, 2016). "Amplification of PIK3CA has been observed in approximately 40% of ovarian cancers, and somatic PIK3CA mutations are detected in 18% of ovarian cancers." (PMID 26959121, 2016). "Collectively, our data suggested that the combination of PI3K and PARP inhibitors represents a promising therapeutic approach for the treatment of PIK3CA mutated ovarian cancers." (PMID 26909613, 2016). "Here we showed that combined inhibition of PI3K and PARP effectively synergized to inhibit proliferation, survival and invasion in the majority of ovarian cancer cell lines harboring PIK3CA mutations, including SKOV3, HEYA8, and IGROV1." (PMID 26909613, 2016). "In the current study, we set out to investigate the inhibitory effect of combination treatment on PIK3CA mutated ovarian cancer cells and the underlying mechanisms that account for the therapeutic effect in in vitro and in vivo." (PMID 26909613, 2016). "The activation of the phosphatidylinositol 3 kinase (PI3K) pathway is frequently deregulated in up to 70 % of ovarian cancers through mechanisms that include amplification of PIK3CA and AKT or inactivating mutations of PTEN." (PMID 26055813, 2015). "In endometrial (and ovarian cancer), PIK3CA mutations are found most frequently on hotspots located on exon 9 and exon 20, with an even distribution between these exons (33% and 45%)." (PMID 24671188, 2014).
ovarian carcinoma (continued). "In ovarian cancer cells, however, PIK3CA gain-of-function mutations and PTEN deficiency were correlated with their response to PI3K pathway inhibitors." (PMID 23459844, 2013). "For example, PIK3CA is mutated in 19% of the ovarian cancer cell lines but in <1% of TCGA HGSOC samples." (PMID 23839242, 2013). "Somatic mutations of PIK3CA have been reported in many cancer types, including liver (36%), breast (8–40%), colon (14–32%), and ovarian cancer (6–12%)." (PMID 23766666, 2013). "For example, analysis of xenografts derived from pancreatic, prostate, ovarian, NSCLC, and ovarian cancer cells revealed that those harboring PIK3CA mutations were among the most sensitive to the AKT inhibitor PHT-427." (PMID 22970424, 2012). "Tumors with a high prevalence of PIK3CA mutations were squamous cell cervical (36%), uterine (25%), breast (21%), colorectal (17%), squamous cell head and neck (15%), and ovarian cancers (11%)." (PMID 21829508, 2011). "Although mutant PIK3CA has been reported to be sufficient to transform normal cells both in vitro and in vivo, PIK3CA mutation exhibits a relatively low frequency in ovarian cancer (4.8–12%) as compared to other cancer types." (PMID 19172191, 2009). "This represents strong genetic evidence that PIK3CA amplification possesses similar oncogenic function as the classical gene mutations in these pathways in ovarian cancer pathogenesis." (PMID 19638206, 2009). "Mutations in the PIK3CA have also been identified in ovarian cancers and though relatively common in endometrioid ovarian carcinomas (EC), are uncommon in serous carcinomas (SC)." (PMID 19638206, 2009). "Numerous recent studies indicate that PIK3CA and downstream pathways are frequently targeted by genomic amplification, mutation or overexpression in solid tumors including ovarian cancer." (PMID 18335034, 2008). "PIK3CA upregulation, amplification and mutation have been widely reported in ovarian cancers and other tumors, which strongly suggests that PIK3CA is a promising therapeutic target." (PMID 18335034, 2008). "In advanced ovarian carcinomas, activating PIK3CA missense mutations were found in only about 4% of the cases." (PMID 19384426, 2007). "Overall, PIK3CA mutation or gene amplification was detected in 30.5% of all ovarian cancers and 45% of the endometrioid and clear cell subtypes." (PMID 19384426, 2007). "Increased copy number of the PIK3CA gene has also been identified in cervical cancer and ovarian cancer, and in the latter case has been shown to be associated with increased expression." (PMID 12942119, 2003). "Alpelisib, already FDA approved for HR-positive, HER2-negative, PIK3CA-mutated advanced or metastatic breast cancer, is being tested in head and neck squamous cell carcinoma, melanoma, multiple myeloma, gastric cancer, pancreatic cancer, and ovarian cancer." (PMID 39808497, 2025). "It is thus likely that these PIK3CA mutations are functionally significant and might act as a first step towards ovarian cancer through the intermediary stage of endometriosis." (PMID 37627318, 2023). "In two previous clinical studies, TAS-117 has shown clinical efficacy in PIK3CA mutated endometrial and ovarian cancers, and in patients with ovarian clear cell carcinoma and had a manageable safety profile across patients with all cancer types enrolled in these studies." (PMID 36039910, 2022). "One patient with ovarian cancer (PIK3CA E545A mutation) who had received 2 lines of previous chemotherapy achieved PR after 5.3 weeks of treatment at the 40 mg dose level and a CR after 29.3 weeks per Response Evaluation Criteria in Solid Tumors (RECIST) 1.1, the DoR was 15.2 months." (PMID 36385120, 2022).
ovarian carcinoma (continued). "De novo resistance to TAS-117 can be overcome by administering a combination treatment comprising chemotherapy, targeted therapy, and immunotherapy and including TAS-117 in earlier treatment lines in patients with breast and ovarian cancers to target PIK3CA E545K, H1047R, and Akt1E17K mutations." (PMID 33723724, 2021). "We investigated PIK3CA mutations (PIK3CAm) for three hotspots (E542K, E545K, H1047R) in eutopic endometrium in patients with ovarian cancer and endometriosis from formalin-fixed paraffin-embedded specimens by laser-capture microdissection and droplet digital PCR." (PMID 34172890, 2021). "Notably, almost 70% of endometrial and ovarian cancers harbor activating mutations of PIK3CA, the gene that encodes the p110α catalytic subunit of PI3K." (PMID 34503172, 2021). "It is interesting to note that PIK3CA is also commonly mutated in endometrial and some ovarian cancers, which could make it a hallmark of gynecological cancers as well as of HPV-driven cancers." (PMID 28771191, 2017). "Thus, the relationship between clinical response to everolimus and PIK3CA mutations, as well as the role of combination therapy, warrants further investigation in clinical trials in ovarian cancer, including those in obese and lean women." (PMID 26959121, 2016). "Given that BKM120 rendered PIK3CA mutated ovarian cancer cells more deficient in HR repair, we hypothesized that combined inhibition of PI3K and PARP may lead to a stronger therapeutic effect than BKM120 as singe-agent." (PMID 26909613, 2016). "In the current study, we found that PI3K inhibition by BKM120 acts synergistically with PARP inhibition in abolishing the growth and survival of PIK3CA mutated ovarian cancer cells (SKOV3, HEYA8, and IGROV1) in in vitro assays as well as in an in vivo model of SKOV3 cells." (PMID 26909613, 2016). "The frequency of PIK3CA mutations in LS-associated ovarian carcinomas is in accordance with the reported high survival, since recent evidence suggests that PIK3CA mutations and the PI3K/AKT pathway activation are associated with a favorable prognosis in ovarian cancer." (PMID 26075229, 2015). "For PIK3CA, its dysfunction arises as a mutation on chromosome 3 that is predominately observed in endometrial, breast, and colorectal cancers or by gene amplification in ovarian cancer." (PMID 23591839, 2013). "Interestingly, mutations typically associated with lower grade (Type I) ovarian cancers such as PIK3CA (0.66% cases mutated) and CTNNB1 (0.6% cases mutated) were also nominated as drivers despite having extremely low frequency." (PMID 23383675, 2012). "There is a mixed report on the incidence of PIK3CA mutation in ovarian cancer." (PMID 19638206, 2009). "Reported incidence of PIK3CA mutation in epithelial ovarian cancer varies from 3.6% to 12%." (PMID 19638206, 2009). "Indeed, PI3K signalling by either PIK3CA or PTEN mutations occurs in 40% of endometrial cancers but in <5% of ovarian cancers." (PMID 19018267, 2008). "Considering that PIK3CA mutations were reported not only in SKOV3 but also in A2780 ovarian-cancer cells, it was inferred that TIE-1 and PI3K p110α expression levels might not always correlate because PIK3CA is independently mutated/amplified in some ovarian-cancer cells." (PMID 32604863, 2020). "Interestingly, the co-existence of KRAS mutation and PIK3CA mutation has also been found in other tumor types such as ovarian carcinoma, suggesting that such co-occurrence might provide a selective advantage to carcinoma cells from various origins." (PMID 23785428, 2013). "This pathway’s alteration includes PIK3CA mutations and a loss of PTEN function, occurring in approximately 12–20% of ovarian cancers." (PMID 39936963, 2025).
ovarian carcinoma (continued). "The results showed that the disease control rate (DCR) was 12.5% and 40.0% in patients with PI3KCA-wt and PIK3CA-m in ovarian cancer, 47.1% and 14.3% in endometrial cancer, 11.1% and 25.0% in cervical cancer." (PMID 40746599, 2025). "This is in agreement with a study of a pan-cancer cohort across 20 different cancer types, including ovarian cancer, in which only 2 patients out of the 1200 analyzed harbored both a PIK3R1 and a PIK3CA mutation." (PMID 39858051, 2025). "Epithelial ovarian cancer exhibits a strong association with defects in PIK3CA and PTEN; it has been reported that the genomic alterations in PIK3CA are found in >20% of all ovarian cancers." (PMID 40370432, 2025). "This histological profile would normally be suggestive of Type I ovarian cancer and the reported mutations of PTEN, PIK3CA and ARID1A genes are consistent with this." (PMID 38940864, 2024). "In the ovarian-carcinoma-investigated patient group, the scientists argue against a simple linear model of PIK3CA gain/amplification followed by PI3K activation and consecutive AKT phosphorylation." (PMID 38391958, 2024). "Two patients had a confirmed partial response to treatment: one with endometrial adenocarcinoma and phosphoinositide-3-kinase regulatory subunit 2 (PIK3R2) alteration, and one with ovarian carcinoma and PIK3CA and PTEN alterations." (PMID 38643311, 2024). "This included confirmed partial responses in two patients: one with endometrial adenocarcinoma harboring a PIK3R2 alteration, and one with ovarian carcinoma harboring a PIK3CA and PTEN alterations." (PMID 38643311, 2024). "PIK3CA gene is confirmed in various cancers, including colorectal, breast, head, and neck, ovarian cancer, and cervical cancers." (PMID 38170269, 2024). "In the COSMIC database PTEN (11%), PIK3CA (11%) and ARID1A (4%) mutations all occur in BRCA1 mutated ovarian cancer." (PMID 38940864, 2024). "Approximately 70% of ovarian cancer patients have aberrations in the PI3K/AKT signaling pathway, and mutations in the gene encoding the catalytic subunit PIK3CA occur in 6–12% of patients." (PMID 38539161, 2024). "Delving into the topic, some data support the role of PIK3CA amplification as an independent factor in predicting the response to chemotherapy in ovarian cancer patients." (PMID 38391958, 2024). "The ORR was 8%, with activity observed in patients with breast and ovarian cancers harboring select PIK3CA and AKT alterations." (PMID 38938274, 2024). "In “TMB-H with MSS” tumors, the ratio of genomic alterations in PIK3CA was the most or the second highest, which was 61.1% in endometrial, 51.4% in cervical, and 31.0% in ovarian cancers." (PMID 38201563, 2023). "In a phase 1 dose-escalation clinical trial, a partial response was observed in a patient with V600E BRAF-mutant melanoma and in a patient with platinum-refractory epithelial ovarian cancer, exhibiting PTEN loss and PIK3CA amplification." (PMID 36765661, 2023). "Endometriosis-associated ovarian cancers (EAOC), namely, clear cell and endometrioid histotypes, are known to harbor recurrent somatic driver mutations, for example, in ARID1A and PIK3CA." (PMID 37789421, 2023). "The wet lab analysis of PRKCG SNP rs1331232028, like many other SNPs in multiple genes, including ERCC1, XPC, PIK3CA, ERBB2 and ERCC2, can be linked to ovarian cancer susceptibility." (PMID 36672978, 2023).